IL23A (interleukin 23 subunit alpha)
Diseases named in the same sentence as IL23A in open-access papers (continued):
Sharing a sentence is not in itself a finding about the gene and the disease.
psoriasis (continued). "In psoriasis, keratinocytes recruit dendritic cells via CCL20, and the production of IL-23A by keratinocytes and dendritic cells recruits and activates IL-17A-producing Th17 cells, CD8+ T cells, innate lymphoid cells (ILC), and γδ T cells." (PMID 31964744, 2020). "Finally, to explore the gene expression profile of IL17A, IL22, and IL23A in relation to other genes expressed in psoriatic plaques, we utilized a machine learning nonlinear dimensionality reduction strategy to visualize the entire psoriasis transcriptome as a 2-dimensional (2D) image." (PMID 31019502, 2019). "The heterodimeric cytokine IL-23, one of the most important mediators in the immunopathogenesis of psoriasis, is composed of the gene products of IL12B (p40) and IL23A (p19)." (PMID 29963046, 2018). "Furthermore, we examined a set of inflammatory cytokines, including IL-17A, IL-23A, IL-1β, TNF-α, IL-6, and IL-22, at the mRNA level in LPS-induced psoriatic keratinocytes, which are closely related to psoriasis in vivo." (PMID 39109246, 2024). "Daphnetin treatment inhibits the proliferation and inflammatory response of human HaCaT keratinocytes and ameliorates imiquimod (IMQ)-induced psoriasis-like skin injury in mice and attenuates the IMQ-induced upregulation of inflammatory cytokines, including IL-6, IL-23A, and IL-17A." (PMID 39544933, 2024). "We observed that there was a substantial proportion of IL23A-expressing keratinocytes regardless of the patient group, i.e., healthy control and psoriasis patients." (PMID 35693818, 2022). "After the psoriasis eruption, eDCs are absent in unchanged skin, while eLC retain high IL-23A expression and continue to respond to TLR stimulation, producing IL-23." (PMID 31963581, 2020). "In addition, HCRG21 reduced the expression levels of Tnf, Il1β, Il6, Il23a, and Il17a in both psoriatic scab and blood cells and inhibited protein production of IL-23-A and MDC levels compared to the values in the IMQ-induced groups, confirming positive anti-psoriasis dynamics." (PMID 41226679, 2025). "In addition, participants diagnosed with psoriasis demonstrated lower RQ values for IL-23A and IL-17RA; however, the obtained results were not statistically significant (p = 0.439585 and p = 0.254683, respectively; Mann–Whitney U test)." (PMID 34945130, 2021). "Because IL22 failed to strongly correlate with IL17A and IL23A, the relationships between IL22 and keratin genes were explored across the four independently acquired RNA-Seq psoriasis datasets." (PMID 31019502, 2019).
colitis (45 papers, 2008 to 2025). Inflammation of the colon. "IL-22 is a required factor for colitis initiation, and its induction is the critical colitogenic response to IL-23a produced by IL-10R-deficient proinflammatory macrophages." (PMID 37373318, 2023). "Moreover, Pin1 KO mice showed downregulation of both Il17 and Il23a expression in the colon, both of which have been implicated in the development of colitis." (PMID 34067858, 2021). "Elevated expression of Il6, Tnfa, and Il23a genes in whole lung tissue was seen in TCRδ-/- mice with colitis, with only the Tnfa gene being mildly elevated in the corresponding C57BL/6 mice." (PMID 37063825, 2023). "IL-23A-responsive ILCs were also found to mediate intestinal pathology in a murine colitis model, and IL-1β-responsive IL-17A-producing ILCs have been reported in the conjunctiva." (PMID 31964744, 2020). "Acer3−/− mice that survived DSS treatment showed more severe colitis, as evidenced by a greater colon shortening, higher levels of inflammatory cytokines (Il-1β, Il-6, Il-23a and Tnf-α), higher MPO activity and more severe pathological manifestations." (PMID 26938296, 2016). "Marked induction of IL1β, IL6, TGFβ and IL23A, genes involved in the differentiation of Th17 cells, was observed in colonic inflammation." (PMID 21144017, 2010). "Our results indicated that the absence of myeloid STING significantly decreased the levels of Il12b, Il12a, and Il23a in colitis and the deletion of STING in DMXAA-treated BMDMs/BMDCs noticeably suppressed pathways related to the IL-12 family and IL-12/IL-23 production." (PMID 39113810, 2024). "The results revealed that Acer3 knockout significantly augmented the colitis-induced increases in the mRNA levels of Il-1β, Il-6, Tnf-α and Il-23a in colon, although Acer3 deficiency did not affect the basal mRNA levels of these inflammatory cytokines." (PMID 26938296, 2016). "We therefore hypothesized that the FoxP3+ population might be related to the resistance to colitis observed in Il23a−/−Rag1−/− mice." (PMID 18400195, 2008). "In addition, Mφs from the colon of Il10ra-deficient mice that spontaneously develop colitis exhibited elevated TLR-induced expression of Il23a, but not Il6 and Tnf." (PMID 30753547, 2019). "Surprisingly, Tgfb1, Il17ra, Il23a, Il6ra, Ror1, Tnf, Tgfbr2, Ccr2, and Il17c were downregulated by cigarette smoke exposure in TNBS-induced colitis Gpr15−/− mice compared with similarly treated Gpr15+/+ mice." (PMID 40957881, 2025). "In contrast, CD11c+ cells from DC-LMP1/CD40xRag1−/−-mice that do not develop colitis do not express elevated levels of Il23a, Il12a, il1b." (PMID 28276457, 2017). "Furthermore, Il23a−/−Rag2−/− mice that received Foxp3−/− naïve T cells, which are unable to differentiate into pTregs, developed severe colitis, whereas those that received WT naïve T cells did not." (PMID 39379604, 2024). "Analysis of cytokines predicted to activate Ifng expressing CD4+ T cells in CPI colitis included IL2 (z score 4.7, P < 1.0 × 10−27), IL7 (z score 3.8, P < 9.8 × 10−19), IL15 (z score 3.4, P < 5.2 × 10−34), IL18 (z-score 2.0, P < 4.0 × 10−25) and IL23A (z-score 2.6, P < 2.1 × 10−31)." (PMID 37872166, 2023). "CX3CR1+ macrophage-derived IL-10 is not required to tame colitis in mice; however, IL-10R expressed by macrophages is essential to prevent fulminant enterocolitis with upregulated pro-inflammatory genes, including Nos2, Il23a, Ccl5, Ccr7, and Saa3." (PMID 33562334, 2021). "However, Il23a was also produced by LP macrophages of F1 mice, which do not develop colitis." (PMID 30653608, 2019). "Taken together, these data indicate that excess Il23a related to HLA-B27-induced UPR and CHOP upregulation is not driving colitis in this model." (PMID 38811719, 2024).
colitis (continued). "It is noteworthy that LPS-induced production of IL-12a, IL-12b, IL-23a, and IL-6 mRNA was not suppressed in colon CD11c+ DCs from Wnt5aMxΔ/Δ mice, which are consistent with the observation that Wnt5aMxΔ/Δ mice showed the phenotypes similar to control mice in DSS-induced colitis." (PMID 26030277, 2015). "However, we have shown previously that Il23a and Il1b mRNA is not induced directly by the LMP1/CD40-transgene, but rather a secondary effect of inflammation, as in B6DC-LMP1/CD40-mice on the Rag-ko background, these cytokines are not present and mice do not develop colitis." (PMID 30653608, 2019).
inflammatory bowel disease (20 papers, 2016 to 2026). A spectrum of small and large bowel inflammatory diseases of unknown etiology. "Additionally, the genes of pro-inflammatory cytokines associated with inflammatory bowel diseases (IBD), such as Il17a, Il23a, and Ifng31 were all upregulated in TCRγδ+CD8αα+ IELs in TGF-β receptor I-deficient mice." (PMID 37253786, 2023).
autoimmune disease (16 papers, 2010 to 2025). A disorder resulting from loss of function or tissue destruction of an organ or multiple organs, arising from humoral or cellular immune responses of the individual to their own tissue constituents. "In addition to the IL-23A gene, some genes related to the IL-23A functions also have been investigated for their possible associations with the risk of autoimmune diseases, such as the variant rs10889677 in the IL-23R gene associated with MS (consensus not reached yet)." (PMID 27893410, 2016). "Interleukin 23 (IL-23), which is a heterodimeric cytokine composed of an IL12B (IL-12p40) subunit and the IL23A (IL-23p19) subunit, is an inflammatory cytokine which plays a vital role in autoimmune diseases and in tumorigenesis." (PMID 31937346, 2020). "It has been widely reported in the literature that many cytokine and chemokine genes (e.g., TNF-a, IL-8, CXCL2, CXCL3, CXCL10, LIF, IL-17C and IL-23A) are the basis of autoimmune disorder pathways that are characterized by inflammation." (PMID 28099447, 2017). "Additionally, a great number of SNPs were found to affect IL23R, a receptor involved in IL23A signaling that is known to be related to AS as well as some autoimmune diseases, and has been previously studied as a possible therapeutic target." (PMID 40507438, 2025). "Currently, some anti-IL-17A (secukinumab, ixekizumab, bimekizumab, brodalumab, etc.)and anti-IL-23A (ustekinumab) monoclonal antibodies are used for the treatment of different autoimmune disorders including IBD, ulcerative colitis, psoriasis arthritis, rheumatoid arthritis, etc.52,53." (PMID 38956309, 2024). "IL-17RB, IL-23a, IL-21, and IL-6 are significantly related to autoimmune diseases." (PMID 35358276, 2022). "It has also been reported that more than 90% of MS patients have humoral responses, and the serum level of IL-23A may reflect autoimmune disease progression and types." (PMID 27893410, 2016). "IDD, deemed to be a kind of autoimmune diseases, may involve IL23A in the pathogenesis." (PMID 27893410, 2016). "IDD, deemed a kind of autoimmune diseases, may involve IL23A in the pathogenesis." (PMID 27893410, 2016).
Arthritis (14 papers, 2010 to 2025). Inflammation of a joint. "Surprisingly, certain genes implicated in arthritis pathogenesis were more than 2-fold higher in arthritic V-KO joints, including NOS2, IL-23a, and IFNA1." (PMID 29216931, 2017). "In the ankle joint, overexpression of several proinflammatory cytokine genes started before arthritis onset, including TNFA from day 6 (p < 0.01) and IL-17A or IL-23A from day 8 (p < 0.05 and p < 0.01)." (PMID 29472591, 2018).
psoriatic arthritis (9 papers, 2020 to 2026). Joint inflammation associated with psoriasis. "Risankizumab, a monoclonal antibody targeting interleukin-23A (IL-23A), is primarily indicated for the treatment of plaque psoriasis, psoriatic arthritis, Crohn’s disease, and ulcerative colitis." (PMID 40343006, 2025). "Similarly, IL-23A serum levels were reported to be significantly and positively correlated with the anxiety scores in psoriatic arthritis patients." (PMID 38956309, 2024).
Crohn disease (8 papers, 2010 to 2026). A gastrointestinal disorder characterized by chronic inflammation involving all layers of the intestinal wall, noncaseating granulomas affecting the intestinal wall and regional lymph nodes, and transmural fibrosis. "Of particular interest is the upregulation of Il-23a, as Il-23 has been shown to be a pro-inflammatory factor and target protein for inhibitory therapy in Crohn’s disease, since it has major effects on Th17 cell differentiation." (PMID 23861820, 2013).
dermatitis (7 papers, 2017 to 2023). An inflammatory process affecting the skin. "Th17 cell-associated genes, (i.e., S100a8, CAMP, BATF, IL-23A, LCN2, and HIF-1α) highly expressed in Nfkbiz−/− mice with dermatitis, were downregulated after antibiotic treatments." (PMID 28740238, 2017).
breast carcinoma (6 papers, 2021 to 2024). "In these cancer cells, the active phosphorylated form of STAT3 interacts directly with the Neh1 and Neh3 domains of NFR2, and the concurrent binding of STAT3 and NRF2 to IL23A promoter accelerates breast cancer cells growth." (PMID 38755517, 2024). "Recently, murine breast cancer cells (4T1) were used to generate a stable cell line expressing IL-23A." (PMID 34093846, 2021). "However, a recent study also demonstrated the overexpression of IL-23A in murine breast cancer 4T1 cells promoted tumor growth via TME modulation." (PMID 34093846, 2021). "The protein products of IL-23A can bind to their receptors in BLBC cells in an autocrine manner, which will amplify the intracellular signals for breast cancer cell proliferation, migration, metastasis, etc.." (PMID 36557902, 2022). "It is worth noting that the survival rate of breast cancer patients with high levels of IL-23A mRNA is worse than that of patients with no or low expression of IL-23A mRNA." (PMID 36557902, 2022).
colorectal cancer (6 papers, 2014 to 2025). A primary or metastatic malignant neoplasm that affects the colon or rectum. "A sequencing of 338 cases of colorectal cancer showed that high-risk tumors exhibit high expression of the IL23A and IL1RN genes and are rich in bacteria such as Alloprevotella." (PMID 33816336, 2021). "Alloprevotella is notably enriched in tumors overexpressing IL23A and IL1RN genes, while Prevotellaceae_UCG‐001 is significantly more abundant in colorectal cancer mice." (PMID 39830908, 2025).
asthma (5 papers, 2017 to 2021). "In asthma macrophages, we observed differential methylation of the IL23A gene which could be seen in the context of macrophage polarization." (PMID 33076907, 2020). "Moreover, DAPP1 expression in the lung was highly positively correlated with a panel of pro-inflammatory cytokines, including several that have been implicated in asthma, such as IL1A, IL7, IL12A, IL17A, IL23A, and IL33." (PMID 31869344, 2019).
candidiasis (5 papers, 2011 to 2024). Infection with the organism Candida. "In sharp contrast to the situation during systemic candidiasis, we detected no reduction in any of the myeloid cell populations in Il23a-/- mice compared to WT controls and the viability was comparable between both genotypes for all subsets." (PMID 31887131, 2019).
periodontitis (5 papers, 2016 to 2024). An acute or chronic inflammatory process that affects the tissues that surround and support the teeth. "Il23a was also detected AG fibroblasts and myeloid cells, with expression present in all epithelial cell subsets at various points in periodontitis development." (PMID 38015204, 2023). "Functional studies using bone marrow chimeric mice from Il23a+/+ and Il23a-/- mice and adoptive transfer studies between these mouse strains demonstrated that non-hematopoietic-cell-derived IL-23 mediates inflammation and disease pathology in experimental periodontitis." (PMID 39253090, 2024).
colon carcinoma (4 papers, 2014 to 2022). "TCGA-COAD database analysis also revealed an association between IL-23A expression and body weight in colon cancer patients (normal vs obese; p < 2.656100E-02)." (PMID 34680308, 2021). "To determine IL-23A expression in colon cancer patient’s tumors, we analyzed the IL-23A gene expression data from the TCGA COAD database." (PMID 34680308, 2021). "TCGA database analyses revealed that IL-23A expression in human colon cancer is strongly correlated with pro-inflammatory molecules and weakly correlated with anti-inflammatory factors." (PMID 34680308, 2021). "Furthermore, IL-23A expressions were highly increased across all the stages of colon cancer as compared to normal tissues." (PMID 34680308, 2021). "In accordance, it is reported that IL-23A is increased in colon cancer." (PMID 34680308, 2021). "We observed a significant increase in the expression level of IL-23A and its receptor IL-23R in colon cancer tissues of humans, and AOM treated rat colon cancer model when compared with matched normal mucosa." (PMID 34680308, 2021). "However, IL-23A expression between the four stages (I, II, III, IV) of colon cancer is not significantly altered." (PMID 34680308, 2021).
glioma (4 papers, 2016 to 2023). A benign or malignant brain and spinal cord tumor that arises from glial cells (astrocytes, oligodendrocytes, ependymal cells). "The Tgfb3, Il6, and Il23a genes were strongly expressed in DCs cocultured with dying glioma cells pulsed with PS-PDT or with MTX (positive control) compared with the control group." (PMID 36539408, 2022).
melanoma (4 papers, 2013 to 2023). A malignant, usually aggressive tumor composed of atypical, neoplastic melanocytes. "Intra-tumor injection of LL-37 significantly increased CXCL5, IL23A, MMP1a, and MMP9 mRNA expression in mouse B16F10 melanoma." (PMID 36980564, 2023). "Most notably, with MC1R, CAT and NOS1 genes in melanoma, HAL and IL23A genes in BCC and HAL and XRCC1 genes in SCC." (PMID 37537768, 2023). "A375 melanoma cells were stimulated with LL-37, and the mRNA expression of CXCL5, IL23A, MMP1, and MMP9 were evaluated in vitro." (PMID 36980564, 2023). "Intra-tumorally administered CRAMP, the mouse ortologe of LL-37, significantly increased the mRNA expression of CXCL5, IL23A, MMP1a, and MMP9 in B16F10 melanoma." (PMID 36980564, 2023). "We found some evidence of GxE interactions with sun exposure, notably, with MC1R, CAT and NOS1 genes in melanoma, HAL and IL23A in BCC and HAL and XRCC1 in SCC." (PMID 37537768, 2023). "Together, these data suggest that the IER2-dependent SASP in B16 melanoma cells includes OPN, CXCL15, CCL5, IL-6, and IL-23a." (PMID 34611309, 2021). "Indeed, peritumoral injection of CRAMP (the mouse ortologe of LL-37) increased the mRNA expression of CXCL5, IL23A, MMP1, and MMP9 in B16F10 melanoma in vivo, suggesting that LL-37 could enhance pro-angiogenesis in melanoma." (PMID 36980564, 2023).
Anxiety (3 papers, 2024 to 2025). Intense feelings of nervousness, tension, or panic often arise in response to interpersonal stresses. "Several studies have linked the IL-17A and IL-23A pathways to anxiety and depression in both human subjects and animal models." (PMID 38956309, 2024). "Regular surveillance of IL-23A levels, particularly in those with a familial background or other predisposing factors for GAD, might facilitate early detection and prompt therapies, potentially halting the development of clinically significant anxiety." (PMID 38956309, 2024).
Autoimmunity (3 papers, 2013 to 2021). The occurrence of an immune reaction against the organism's own cells or tissues. "The upregulated transcript levels for IL-23A and CCL3 were found associated with high incidence of autoimmunity." (PMID 31781116, 2019).
ileitis (3 papers, 2014 to 2025). "Curdlan-induced goblet cell loss and ileitis occur after P.g. or L.m. monoassociation, even though L.m. has greater capacity than P.g. to stimulate low levels of Il23a, Grp78, Tjp1, mucin, and ZO-1 in naive mice." (PMID 40762957, 2025). "Intriguingly, susceptibility to ileitis in SKG mice could be mitigated by the ASF miniconsortium, which regulated Il23a and ER stress and upregulated Il10, preserving goblet cells and ZO-1+ tight junctions." (PMID 40762957, 2025). "ASF-SKG ileum expressed higher levels of Ocln and lower Reg3g and Reg3b than GF or monoassociated SKG ileum, consistent with their lack of ileitis and lower ER stress and Il23a levels." (PMID 40762957, 2025).
leprosy (3 papers, 2013 to 2020). Leprosy is a chronic infectious disease affecting primarily the skin and peripheral nervous system. "Moreover, IL-23A was significantly higher in BT (p<0.0003, Mean ΔCT ±SD ΔCt: 4.7±0.7) as compared to LL (Mean ΔCt ±SD: 7.26±1.09) indicating differential expression within the two leprosy types." (PMID 23936569, 2013).
prostate carcinoma (3 papers, 2021 to 2025). A carcinoma that arises from epithelial cells of the prostate gland. "Using this resource, we readily identify, for example, that a subpopulation of very advanced prostate cancer tissues expresses high levels of IL23A, a cytokine recently described to mediate castration resistance in prostate cancer." (PMID 34857732, 2021). "In prostate cancer, apolipoprotein E (APOE) in the TME binds to TREM2 on macrophages and promotes androgen receptor (AR) expression, which further upregulates the transcription of immune mediators such as IL-10, TGF-β1, IL-23A, and CCL2." (PMID 41417432, 2025).